NR4A2 (nuclear receptor subfamily 4 group A member 2)
Diseases named in the same sentence as NR4A2 in open-access papers (continued):
Sharing a sentence is not in itself a finding about the gene and the disease.
cancer (64 papers, 2008 to 2025). A tumor composed of atypical neoplastic, often pleomorphic cells that invade other tissues. "High expression of NR4A2 is closely associated with cancer progression and promoting cancer cell migration." (PMID 33328994, 2020). "NR4A1 and NR4A2 are also two early responding genes associated with cancer and chronic inflammatory diseases, including that affecting the kidneys." (PMID 31392215, 2019). "NR4A2 is a nuclear transcription factor that, when aberrantly regulated, is known to promote cancer progression by enhancing autophagy and inducing chemotherapy resistance." (PMID 41343608, 2025). "Although a notable protein-coding gene, NR4A2 (Nuclear Receptor 4A2), is located immediately adjacent to the defined 1Mb boundary, its established function is highly pertinent to cancer biology." (PMID 41343608, 2025). "In this regard, several reports have described the transcriptional regulation of NR4A2 by miRNA in DAergic neurons, cell death and cancer." (PMID 41009723, 2025). "The potent antitumorigenic activity of the DIM-3,5 analogs are due to several factors including their activity as dual NR4A1/NR4A2 inverse agonists that inhibit the pro-oncogenic pathway/genes, such as PD-L1, regulated by both receptors in cancer cells." (PMID 40313760, 2025). "In solid tumors, NR4A1 and NR4A2 are negative prognostic factors, they exhibit pro-oncogenic activities, and these can be inhibited by bis-indole derived compounds (CDIMs) which bind NR4A1 and NR4A2 and act as antagonists in cancer cells." (PMID 37175855, 2023). "Nuclear receptor subfamily 4 group A member 2 (NR4A2) is an orphan nuclear receptor that is upregulated in cancer and is involved in malignant biological properties." (PMID 32219093, 2020). "Multiple studies have revealed that NR4A2 functioned as a carcinogene in several cancers, and indicated poor prognosis in NPC patients." (PMID 32368184, 2020). "NR4A2 participates in stress-induced apoptosis of various cancer cells with different functions, indicating that it has a cell-specific role in apoptosis." (PMID 29531824, 2018). "Increased expression and function of NR4A2 have been attributed to various signaling pathways, but little is known about microRNA (miRNA) regulation of NR4A2 in cancer." (PMID 27121375, 2016). "Nuclear receptor subfamily 4 group A member 2 (NR4A2) is an orphan nuclear receptor that is over-expressed in cancer and promotes cell proliferation, migration, transformation, and chemoresistance." (PMID 27121375, 2016). "Of note, in the cancer under study here, the mRNA level of NR4A2 was overexpressed 10-fold compared to bone and 3-fold compared to muscle." (PMID 25861239, 2015). "Compared to normal gastric oxyntic mucosa the expression pattern of NR4A2 seemed to be changed in both cancer types." (PMID 24086717, 2013). "Similarly, NR4A2 has been characterized as pro-oncogenic in various solid tumor cell lines, contributing to cancer cell proliferation, survival, and metastasis." (PMID 40361912, 2025). "Moreover, different miRNAs have been identified that directly and negatively regulate NR4A2 expression in cancer." (PMID 41009723, 2025). "This module included a number of immediate early and growth factor response genes and overlapped with modules previously identified for SDF1 responses in PBs (genes such as CD69 and NR4A2) and growth factor responses in cancer (genes such as EGR1/3, FOS, FOSB, and IER2)." (PMID 36130130, 2022). "Accumulating researches stated that NR4A2 played an oncogenic role in cancers." (PMID 32368184, 2020). "NR4A2 is involved in cancer progression through a mechanism that has yet to be fully described." (PMID 27121375, 2016). "In this study we throw light on the dichotomous role of NR4A2 in cancer." (PMID 24086717, 2013).
cancer (continued). "However, the biological actions of NR4A2 have been elucidated in other types of cancers." (PMID 35965537, 2022). "In this study, to determine whether human NR4A2 is regulated by miRNAs and investigate its oncogenic-like role, we used an miRNA screening approach to identify cancer-relevant posttranscriptional regulatory networks of NR4A2, a subject that has not been fully explored." (PMID 27121375, 2016). "The NR4A family (NR4A1/NUR77, NR4A2/NURR1, and NR4A3/NOR1) regulates mitochondrial function, energy metabolism, and inflammation, with implications in CVD, neurodegeneration, and cancer." (PMID 40926269, 2025). "Although there were some binding-assay-specific differences in their KD values and KD(NR4A1)/KD(NR4A2) ratios, each of the DIM-3,5 and DIM8-3,5 analogs bound both receptors and are dual receptor ligands that act as inverse agonists in cancer cell lines." (PMID 38540704, 2024). "In summary, this study describes a series of structurally related bis-indole compounds that bind both NR4A1 and NR4A2 and are dual receptor ligands that act as inverse NR4A1/2 agonists in cancer cell lines." (PMID 38540704, 2024). "To identify putative miRNAs capable of regulating NR4A2 through its 3′ UTR, we assessed the effects of 75 cancer-relevant miRNAs by using a luciferase reporter system." (PMID 27121375, 2016). "NR4A2 is a family member of AR (NR3C4), which is known to be activated downstream of the MAPK pathway in cancer and directly interacts with NFκB (specifically the REL subunit), as correctly predicted for NR4A2." (PMID 27078000, 2016). "Moreover, focal CNA amplifications encompassed genomic peaks that harbored canonical cancer genes including those found at HPV-integrated hotspots (MYC, MYCN, MYCL, SOX2, NR4A2, and ANKRD12), and others (CCNE1, SMAD2, BCL2L1, and GNAS)." (PMID 36216793, 2022). "In our previous studies, we also showed that LKB1-deficiency led to CRTC activation of many CREB-dependent genes, including NR4A2, PTGS2 (aka COX-2), LYPD3, INSL4, and LINC00473, which play important roles in cancer cell growth, survival or invasive properties." (PMID 34142658, 2021). "Furthermore, pairwise Pearson correlation for 21/33 cancer types revealed recurrent correlation between the expression patterns for multiple class I-III NRs and retinoid X receptors (RXRs), as well as, strong positive correlation between class IV NRs (NR4A1, NR4A2, NR4A3) in 20/21 pan-cancers." (PMID 32024906, 2020). "In several cancer- and non-cancer-related diseases, NR4A1 and NR4A2 are over-expressed and are targetable with receptor agonists or inverse agonists to ameliorate disease, and there are increasing studies on development of new NR4A ligands." (PMID 40332813, 2025). "It was demonstrated that the NR4A family has a role in T cell development from thymic differentiation to peripheral response against infections and cancer; the overexpression of NR4A1 and NR4A3, but not NR4A2, induces thymocyte apoptosis in vivo." (PMID 35407632, 2022). "Intriguingly, evidence of NR crosstalk was found between NR class IV genes (NR4A1, NR4A2, NR4A3) in 20/21 cancer types (absent in SKCM)." (PMID 32024906, 2020). "Hence, modulation of NR4A1 and NR4A2 expression by Rasd1 and NonO could have a major impact on the circadian control, and disruption of this process can give rise to metabolic diseases and cancer development." (PMID 21915321, 2011).
neurodegenerative disease (27 papers, 2013 to 2026). A disorder of the central nervous system characterized by gradual and progressive loss of neural tissue and neurologic function. "NR4A2 plays a pivotal role in the development of nigrostriatal dopamine neurons and is therefore implicated in the pathogenesis of neurodegenerative diseases linked to the midbrain dopamine system." (PMID 41019763, 2025). "Several animal models and clinical studies have linked NR4A2 gene dysregulation to neurodegenerative diseases and psychiatric disorders." (PMID 41009723, 2025). "As NR4A2 is a transcription factor belonging to the steroid hormone receptor class associated with autoimmune, neurodevelopmental, and neurodegenerative diseases, and is increased in neurons of pwMS, it qualified as a potential regulator of neuronal integrity." (PMID 39145444, 2024). "Moreover, research in animal models and clinical trials has suggested an association between reduced NR4A2 gene expression and some neurodegenerative diseases and psychiatric disorders." (PMID 41009723, 2025). "In the context of neurodegenerative diseases and psychiatric disorders, it is therefore important to highlight the role of the NR4A2 gene and its gene regulation." (PMID 41009723, 2025). "Based on these documented roles, gene- and cell-based therapies targeting NR4A2 have become promising candidates for the treatment of neurodegenerative disease." (PMID 37887305, 2023). "In this neurodegenerative disease it has been previously reported that the levels of expression of the NR4A2 gene were decreased in 3C homozygous compared to the other genotypes of the rs34884856 promoter variant." (PMID 33563249, 2021). "These lines of research could open the way for personalized treatment of neurodegenerative diseases and psychiatric disorders, reinforcing the role of NR4A2 in the field of translational medicine." (PMID 41009723, 2025). "Taken together, our data add to the growing body of evidence linking NR4A2 to neurodegenerative disease and highlight two novel means by which disease progression may be targeted via FUS and lnc-ERMN." (PMID 37887305, 2023). "Moreover, NR4A2 positively regulates the survival of dopaminergic and other neurons and has therefore been proposed as a neuroprotective target for the treatment of neurodegenerative diseases." (PMID 36835547, 2023). "The ligand-activated transcription factor nuclear receptor related 1 (Nurr1, NR4A2) is considered as a promising target in neurodegenerative diseases for its neuroprotective and anti-neuroinflammatory activities." (PMID 41503280, 2026).
neurological disorders (16 papers, 2013 to 2025). "However, the identification of synthetic small molecules that could modulate NR4A2 transcriptional activity opens the possibility to provide target-based therapies for these neurological diseases." (PMID 38791237, 2024). "A nuclear receptor Nurr1 (NR4A2) is known to exert anti-inflammatory and neuroprotective effects in several neurological disorders." (PMID 38704311, 2024).
infection (15 papers, 2012 to 2025). The state of being infected such as from the introduction of a foreign agent such as serum, vaccine, antigenic substance or organism. "To further confirm the infection of DA neurons, we analyzed both TH and NR4A2 positive cells as well as all cells." (PMID 38237586, 2024). "The expression levels of Nr4a2, Ace2, and Tmprss2 proteins, as well as the infection level of Omicron BA.5 pseudovirus, were significantly higher in the lung and testis tissues of BaP‐treated hamsters compared to dimethyl sulfoxide (DMSO)‐control hamsters." (PMID 37428471, 2023). "In the orphan NR family, all three members of Nurr family (Nr4a1, Nr4a2 and Nr4a3) exhibited repression while Rora was upregulated during later stages of infection." (PMID 29396519, 2018). "Quantitative PCR data revealed that MRSA-infection predominantly induced expression of TLRs 1, 2, 6, NR4A2, and inflammatory cytokines IL-8, IL-6, TNFα in hMSCs." (PMID 24661536, 2014). "At 48 h post infection, when the equilibrium between bacteria and macrophages was established, few NRs that did not respond during early infection (0 h) showed elevated levels (Ppard, Rxra, Nr4a2, and Rora)." (PMID 29396519, 2018). "As IL-8 is the target gene for NR4A2, our data support the notion that NR4A2 could be a critical regulator of those gene involved in proliferation in infection-mediated TLR-activated hMSCs." (PMID 24661536, 2014). "1,25(OH)2D3-VDR may exhibits its anti-inflammatory properties in MRSA-stimulated infection by inhibiting nuclear translocation of NF-kB-p65 and transcripts of IL-8, IL-6, TNFα, and NR4A2 in hMSCs." (PMID 24661536, 2014). "NR4A2 knockdown or interferon‐λ2/λ3 stimulation downregulates the expression of NR4A2, ACE2, and TMPRSS2, thereby inhibiting the infection." (PMID 37428471, 2023). "Our RNA-seq analysis shows that several inhibitors of the NF-kB and MAPK signaling pathways were significantly down-regulated 36 days after infection, including NFKBID, NFKBIZ, DUSP-1, -2, NR4A2, and tristetraprolin (TTP or ZFP36)." (PMID 33324683, 2020). "This was supported by the upregulation of the NF-kB inhibitor genes NFKBIA and NFKBIZ, the AP-1 transcription factor complex genes FOS, JUN, FOSB and JUNB as well as other NF-kB target genes such as TNFAIP3, RELB, NR4A2, DUSP1 and CD69 in response to infection." (PMID 37700317, 2023). "Knockdown of NR4A2 and stimulation with IFN‐λ3 significantly inhibited the infection of wild‐type SARS‐CoV‐2 and Omicron BA.5 pseudoviruses, whereas nicotine did not significantly affect infection." (PMID 37428471, 2023).
brain disorder (7 papers, 2011 to 2024). A disease affecting the brain or part of the brain. "NR4A2, also known as Nurr1, encodes a member of the steroid-thyroid hormone-retinoid receptor superfamily that is expressed in a complex pattern in the cortex, which may be different in mouse and primates, and could be involved in several human brain diseases." (PMID 21445258, 2011). "All these studies clearly show that the involvement of Nr4a2 in brain diseases expands beyond PD and point out this transcription factor as a promising candidate for the development of novel therapeutic approaches." (PMID 34880728, 2021). "Future work should provide solid grounds to determine the precise contribution of Nr4a2 to each brain disorder." (PMID 34880728, 2021). "The identification of synthetic small molecules that could modulate Nr4a2 transcriptional activity opens the possibility to provide target-based therapies for brain diseases related to Nr4a2." (PMID 34880728, 2021).
neurodevelopmental disorder (7 papers, 2020 to 2025). A behavioral and cognitive disorder with onset during the developmental period that involves impaired or aberrant development of intellectual, motor, or social functions. "Pathogenic variants in NR4A2 are associated with neurodevelopmental disorders including intellectual developmental disorder with language impairment and early-onset dopa-responsive dystonia-parkinsonism (IDLDP)." (PMID 41019763, 2025). "To date, 43 pathogenic NR4A2 variants have been described and are strongly associated with different neurodevelopmental disorders." (PMID 40564942, 2025). "Our research further confirms that NR4A2 is a disease-causing gene of neurodevelopmental disorders and suggests alterations in different domains of NR4A2 cause various severity of symptoms." (PMID 35992907, 2022).
psychiatric disorder (7 papers, 2015 to 2025). A disorder characterized by behavioral and/or psychological abnormalities, often accompanied by physical symptoms. "In this manner, alterations in the expression of the NR4A2 gene have been associated with various neurological and psychiatric diseases." (PMID 41009723, 2025). "This represents a valuable contribution to the search for drugs in complex neurological and psychiatric diseases associated with NR4A2 dysfunction." (PMID 41009723, 2025). "The mechanisms that regulate NR4A2 gene expression have significant therapeutic potential for the treatment of neurodegenerative and psychiatric diseases." (PMID 41009723, 2025). "NR4A2 is a promising neuroprotective and anti-inflammatory target in neurodegenerative and psychiatric diseases." (PMID 41009723, 2025). "Given its importance, understanding the mechanisms that regulate NR4A2 gene expression and identifying potential therapeutic targets for neurological diseases and psychiatric disorders is a priority." (PMID 41009723, 2025). "Finally, we describe the dysregulation of NR4A2 gene expression in various neurodegenerative and psychiatric diseases." (PMID 41009723, 2025). "Moreover, the relationship between Nr4a2 and some psychiatric diseases has been already established." (PMID 34880728, 2021). "These TRs, such as transcription cofactors and chromatin regulators, may mediate regulatory signals between the promoters and distal enhancers of the NR4A2 gene, thereby regulating its expression, particularly in the context of neurodegenerative and psychiatric diseases." (PMID 41009723, 2025). "Therefore, we can conclude that NR4A2 is a potential therapeutic target for neurological and/or psychiatric diseases, due to its key role in the survival of dopaminergic neurons, as well as in the regulation of neuroinflammation and neuronal plasticity, among other functions." (PMID 41009723, 2025).
metabolic disease (3 papers, 2011 to 2020). A congenital disorder (due to inherited enzyme abnormality) or acquired (due to failure of a metabolically important organ) disorder resulting from an abnormal metabolic process. "A member of the nerve growth factor I-B Nurr1 (NR4A2) is another NR4A receptor, which has been implicated, in various hormonal, physiological and pathophysiological processes including cardiovascular, neurological and metabolic diseases, inflammation and oncogenesis." (PMID 23950896, 2013).
adenocarcinoma (2 papers, 2013 to 2022). A common cancer characterized by the presence of malignant glandular cells. "Therefore, proteins such as the transcription factor NR4A2 whose suppression has been linked to the gastrointestinal inflammation and adenocarcinoma, and the A20 protein, an NFκB inhibitor may indicate promising candidates for further analysis on Tipα activity and pathogenesis." (PMID 35237167, 2022). "In this study we demonstrate that gastrin induces Nuclear Receptor 4A2 (NR4A2) expression in the adenocarcinoma cell lines AR42J and AGS-GR, which both possess the gastrin/CCK2 receptor." (PMID 24086717, 2013).
movement disorder (2 papers, 2024 to 2025). Neurological conditions resulting in abnormal voluntary or involuntary movement, which may impact the speed, fluency, quality and ease of movement. "Patients with NR4A2 (likely) pathogenic variants and movement disorder symptoms reported to date." (PMID 41019763, 2025).
heart diseases (1 paper, 2024). "Although NR4A2 is associated with the pathogenesis of various heart diseases, the role of NR4A2 in I/R heart injury is unclear." (PMID 38542280, 2024). "Previous studies have suggested that NR4A2 regulates the pathogenesis of various heart diseases, including diabetic cardiomyopathy, cardiac hypertrophy, left ventricular dilation, and heart failure by modulating the autophagy flux, cardiac metabolism, and hemodynamics." (PMID 38542280, 2024).
immune dysfunction (1 paper, 2022). "The immune dysfunction mainly contributes to the pathogenesis of PCHD, and three ceRNA networks of CD83, CXCL8, and NR4A2 may be potential candidate biomarkers for early diagnosis and treatment targets of PCHD." (PMID 36093144, 2022).
intestinal disorder (1 paper, 2019). A non-neoplastic or neoplastic disorder that affects the small or large intestine. "Three SNPs (g.36224286 > C/T, g.36225242 > G/T and g.36225278 > C/T) were annotated in the NR4A2 gene, a positional candidate gene for INTES and these genetic variants might be responsible for changes in glucose levels driving the occurrence of intestinal disorders." (PMID 31438838, 2019).